FBF1 (Fas binding factor 1)
Description:
Keratin-binding protein required for epithelial cell polarization. Involved in apical junction complex (AJC) assembly via its interaction with PARD3. Required for ciliogenesis.
Synonyms: FBF-1; ALB; KIAA1863; FLJ00103
Tractability: PROTAC: UniProt records ubiquitination sites on it.
Gene: Protein-coding gene on chromosome 17 (75,909,574 to 75,941,140, reverse strand). Ensembl gene ENSG00000188878.
Subcellular location: Cytoplasm, cytoskeleton, microtubule organizing center, centrosome, centriole; Cytoplasm, cytoskeleton, spindle pole; Cell junction
Subcellular location (Human Protein Atlas): Basal body; Centrosome; Primary cilium
Pathways (Reactome):
Organelle biogenesis and maintenance: Anchoring of the basal body to the plasma membrane
Gene Ontology:
Molecular function: protein binding
Biological process: apical junction assembly; cilium assembly; establishment of epithelial cell polarity
Cellular component: apical junction complex; centriole; centrosome; ciliary basal body; ciliary transition fiber; keratin filament; spindle pole; cytosol; anchoring junction
Genetic constraint (gnomAD): Loss-of-function variants: 121 observed, 124.19 expected, observed/expected ratio (o/e) 0.97, 90% interval 0.84 to 1.13. The upper end of that interval is the gene's LOEUF score, 1.13, which puts it in group 4 of 6, group 1 being the genes least tolerant of losing a copy. Missense variants: 1,448 observed, 1,402.6 expected, observed/expected ratio (o/e) 1.03, 90% interval 0.99 to 1.08. Synonymous variants: 601 observed, 561.93 expected, observed/expected ratio (o/e) 1.07, 90% interval 1 to 1.14.
Homologues: Orthologues: chimpanzee FBF1 (98% identical), macaque FBF1 (93% identical), dog FBF1 (76% identical), pig FBF1 (73% identical), guinea pig FBF1 (68% identical), mouse Fbf1 (67% identical), rat Fbf1 (66% identical), tropical clawed frog fbf1 (44% identical).
Diseases named in the same sentence as FBF1 in open-access papers:
FBF1 is named in the same sentence as 17 diseases in open-access papers, as found by Europe PMC text mining. Sharing a sentence is not in itself a finding about the gene and the disease. The quoted sentences say what the papers report.
Arthritis (1 paper, 2024). Inflammation of a joint. "Several studies have investigated males with FBF1 mutation carriers also related to arthritis diseases, including those under rheumatoid arthritis conditions, which revealed the possibility of conferring the gene mutation to the next generation of offspring." (PMID 38963098, 2024). "The FBF1 is an inheritable arthritis disease phenotype that includes rheumatoid arthritis." (PMID 38963098, 2024).
ciliopathies (1 paper, 2020). "More importantly, the conserved function of these proteins across ciliated species and their tight correlation with ciliopathies suggest that FBF1-related TF is likely the most important subdomain required for cilia gating." (PMID 32366837, 2020).
Hearing impairment (1 paper, 2021). A decreased magnitude of the sensory perception of sound. "As we have described, the severity of the hearing impairment for carriers of the highly penetrant variants in LOXHD1 and FBF1 varies from mild to profound." (PMID 34108613, 2021). "Five of the variants that have rare genotypes with large effects are at loci that have not been reported for any type of hearing impairment: FBF1, FSCN2, C10orf90, SH2D4B, and TBX2." (PMID 34108613, 2021).
melanoma (1 paper, 2023). A malignant, usually aggressive tumor composed of atypical, neoplastic melanocytes. "Associations with the presence of TERT promoter mutations revealed an overlap of 30 genes in the three bulk RNA-seq cohorts (in melanoma and across entities), of which six genes were consistently up- or down-regulated (up: ARL17A, FBF1, KAZALD1, PRAF2; down: PLEKHB2, RASGRP3)." (PMID 37418389, 2023).
rheumatoid arthritis (1 paper, 2024). A chronic, systemic autoimmune disorder characterized by inflammation in the synovial membranes and articular surfaces. "Consequently, several underlying hypotheses suggest that an autosomal recessive inheritance syndrome, such as HYDS1 in a male carrier of FBF1 mutation, may transfer the mutation to progeny with the presence of a rheumatoid arthritis carrier." (PMID 38963098, 2024).
tumor (5 papers, 2016 to 2022). "In vivo, overexpression of LST-1 or SYGL-1 proteins in the presence of FBF-1 (a key partner of mRNA repression in stem cells) generates an overproliferation phenotype and leads to germline tumor formation." (PMID 35469833, 2022). "The importance of FBF1 and BRSK2 in tumor initiation or progression has yet to be shown, but it is known that these genes are required for the establishment of epithelial cell polarity." (PMID 27014907, 2016). "In an attempt to see their FBF-independent function, we tested fbf-1 fbf-2 sygl-1(ubiq) and fbf-1 fbf-2 lst-1(ubiq) animals for tumor formation at 25°C, because at this temperature, the FBF requirement is relieved in that fbf-1 fbf-2 mutants can maintain a small GSC pool." (PMID 29232700, 2017).
autosomal recessive disease (1 paper, 2024). Autosomal recessive form of disease. "Exercise has no impact on novel-rno-miRNA-1135 targeted for FBF1 in autosomal recessive disease." (PMID 38963098, 2024).
FBF1 also shares sentences with these, for which no sentence is quoted: cancer (2 papers); head and neck cancer (1); Hydrolethalus Syndrome 1 (1); Immunodeficiency (1); Leukoaraiosis (1); neurologic diseases (1); non-small and small-cell lung cancers (1); prostate carcinoma (1); prostate tumors (1); rectal carcinoma (1).